HMGB1 (high mobility group box 1)
Diseases named in the same sentence as HMGB1 in open-access papers (continued):
Sharing a sentence is not in itself a finding about the gene and the disease.
breast carcinoma (continued). "The lack of autophagy and reduced HMGB1 expression have been associated with extremely poor prognosis in breast cancer specimens and potentially with adverse effects on immune surveillance by anticancer drugs, and thereby with the promotion of tumor progression." (PMID 34638242, 2021). "Considering the nature of HMGB1 as a cytokine and the paracrine model by which CAFs might drive the progression of breast cancer, we further demonstrated that activation of GPR30 in CAFs induced resistance to TAM in MCF-7 cells through the paracrine action of HMGB1." (PMID 34182538, 2021). "Therefore, HMGB1-induced autophagy might be a promising landmark in tumor growth and for the progression of endocrine therapies for breast cancer." (PMID 34182538, 2021). "So we hypothesize that HN1L regulates the metastasis of breast cancer cell by HMGB1." (PMID 33191617, 2021). "Previous studies have shown that HMGB1 expression in tumour tissue is significantly higher than that in their normal counterparts and that HMGB1 levels correlate positively with tumour size, stage and prognosis of cancers, such as breast carcinoma 36, hepatocellular carcinoma 37, and lung cancer." (PMID 34539874, 2021). "This study may help to better understand the molecular mechanisms of drug resistance in breast cancer, and it may imply that overexpression of miR-129-5p alone or in conjunction with HMGB1 interference, is a promising strategy to combat multidrug resistance in breast cancer." (PMID 31664305, 2019). "Furthermore, miR-129-5p/HMGB1/autophagy might be developed as a novel method for overcoming Taxol resistance in breast cancer." (PMID 31664305, 2019). "Overexpression of HMGB1 in tumor tissue and increased HMGB1 serum level are near-universal in virtually every examined type of cancer, including colon carcinoma, hepatoma, breast cancer (BC), pancreatic cancer, melanoma, ovarian cancer, and mesothelioma, indicating a carcinogenic role of HMGB1." (PMID 30049847, 2018). "We also analyzed if DHA could trigger HMGB1 translocation in breast cancer cells." (PMID 29386662, 2018). "For instance, HMGB1 could mediate the chemotherapy resistance in breast cancer." (PMID 28376901, 2017). "Furthermore, we could show recently that the level of circulating HMGB1 increases in breast cancer patients in response to the first cycle of epirubicin/docetaxel combination therapy." (PMID 28861714, 2017). "In this case–control study, we examined the genetic predisposition of six well‐defined polymorphisms in HMGB1/RAGE pathway to breast cancer in a large Han Chinese population, and we observed a significant association between RAGE gene rs1800624 polymorphism and breast cancer." (PMID 27241711, 2016). "However, according to the research, intercellular HMGB1 also could interact with RB, a tumor suppressor in breast cancer, and increase genome instability and autophagy." (PMID 26393575, 2015). "Indeed, a classical DAMP, HMGB1 was enriched specifically in breast cancer derived monocytes." (PMID 25992611, 2015). "Hence we hypothesized that stromal fibroblasts in breast cancer may also play a similar role in chemoresistance through the up-regulation of HMGB1 in cancer cells during chemotherapy-mediated cell death." (PMID 25512109, 2014). "It has been shown that HMGB1 secreted by breast cancer cells can activate fibroblasts via the RAGE/aerobic glycolysis pathway, and the activated fibroblasts, in turn, promote breast cancer cell metastasis by increasing lactate production." (PMID 39849606, 2025). "In this study, we aimed to investigate the involvement of cytoplasmic HMGB1 in the STAT3 signaling and expression of PD-L1 in breast cancer." (PMID 40389855, 2025). "We also confirmed that HMGB1-induced EMT and the increased migration of breast cancer cells in vitro depend on RAGE expression levels." (PMID 40277915, 2025).
breast carcinoma (continued). "In breast cancer, macrophage-derived CXCL1 activates an IGF1R/STAT3/HMGB1 axis that promotes autophagy-mediated paclitaxel resistance and inhibits apoptosis." (PMID 41465435, 2025). "The natural compound triptolide was also shown to suppress breast cancer growth by directly reducing HMGB1 expression and secretion, thereby inhibiting downstream TLR4/NF-κB signaling and enhancing the efficacy of other HMGB1 inhibitors like EP." (PMID 41465435, 2025). "CXCL1 knockdown in TAMs demonstrated a remarkable chemosensitizing effect on breast cancer xenografts, along with blockage of IGF1R/STAT3/HMGB1 signaling in vivo." (PMID 39394189, 2024). "Collectively, our research highlights the important role of TAMs/CXCL1 in mediating breast cancer chemoresistance through the regulation of autophagy, and proposes IGF1/IGF1R as a potential upstream signaling that governs autophagy via STAT3/HMGB1 activation." (PMID 39394189, 2024). "Particularly, histone-HA NPs can effectively deliver Ce6 and HMGB1-siRNA to cancerous cells to achieve robust PDT and gene editing, resulting in a significant breast cancer cell suppression effect." (PMID 38791462, 2024). "In breast cancer cells (MCF-7), HMGB1 promoted tumor vessel formation and enhances cancer cell migration by regulating HIF1A through the phosphatidylinositol 3 kinase/protein kinase B (PI3K/AKT) signaling pathway." (PMID 38725632, 2024). "Several DAMPs have been linked to postoperative immune suppression and infectious complications (High mobility group box 1 (HMGB1) and Heat shock protein 70 (HSP70)), and breast cancer (alarmins S100A8/A9 and S100A12)." (PMID 38468349, 2024). "Breast cancer tissues in TMA were utilized to investigate the clinical significance of CXCL1 and its relevance with HMGB1, IGF1R, and CD163 expressions." (PMID 39394189, 2024). "Quercetin, a well-known anti-cancer agent, is a natural flavonoid that inhibits the expression of HMGB1 and RAGE in human breast cancer at the transcription and translation levels." (PMID 38529373, 2024). "Our study found that DSF/Cu treatment increases apoptosis in the breast cancer cells, and ICD-related indicators including CARL, HMGB1, HSP70, and HSP90 were upregulated." (PMID 38370371, 2024). "For instance, HMGB1 secreted by breast cancer cells promotes fibroblast activation via RAGE/aerobic glycolysis, and activated fibroblasts enhance breast cancer cell metastasis through increased lactate levels." (PMID 37496657, 2023). "In breast cancer cells, TLR2 is overexpressed and can be activated by endogenous ligands such as HSPs, HMGB1 and other DAMPs, or by exogenous ligands derived from pathogens, like bacterial lipoproteins." (PMID 38203626, 2023). "To confirm that the antitumor immunity in the 4T1 breast cancer mouse model was induced by GSDMBNT mRNA@LNP-mediated pyroptosis, we investigated the expression of ICD biomarkers (CRT and HMGB1) and pyroptosis-related cytokines (IL-1β and IL-18)." (PMID 37454146, 2023). "Reciprocally, a recent study demonstrated that extra-cellular HMGB1/RAGE promote anaerobic glycolysis of fibroblasts that is required for their activation by breast cancer cells, leading to breast cancer cell metastasis." (PMID 36982351, 2023). "HMGB1 and its receptor TLR2 have a crucial role in mammary cancer stem cell self-renewal, tumorigenesis, and metastatic ability." (PMID 36982351, 2023). "Mechanistically, cirCHIPK3 serves as a sponge for miR-193a, thereby reactivating HMGB1/PI3K/AKT signaling to promote proliferation, migration and invasion of breast cancer cells." (PMID 35637945, 2022). "This study aimed to investigate the mechanism of HMGB1 through receptors for advanced glycation end products (RAGE) on cell migration/invasion and PD-L1 expression in breast cancer cells." (PMID 35610613, 2022). "We also obtained high HMGB1 expression with better OS and PPS for breast cancer, gastric cancer, and lung cancer." (PMID 36230798, 2022).
breast carcinoma (continued). "The differences in HMGB1 phosphorylation levels were compared between normal tissue and primary tumour tissues using CPTAC datasets for four types of tumours (breast cancer, clear cell carcinoma, LUAD and UCEC)." (PMID 35765707, 2022). "In in vitro studies, ALA blocks TGF-beta, HMGB1, ERK1/2, and AKT signaling, leading to the inhibition of epithelial-mesenchymal transition and the sensitization of breast cancer cells to ionizing radiation." (PMID 35564468, 2022). "In contrast, GPER1 expression has been associated with reduced response or resistance to tamoxifen therapy in patients with breast cancer, mediated by regulating HMGB1 (high mobility group box 1)." (PMID 36060947, 2022). "Further, the signaling pathway went downstream to high mobility group box-1 (HMGB1)/phosphoinositide-3-kinase (PI3K)/AKT and the proliferative and metastatic abilities of breast cancer cells were enhanced as a consequence." (PMID 36292157, 2022). "On 4T1 breast cancer cells, BP-PTT modulates the most crucial markers of ICD, namely, exposure of calreticulin (CRT) and release of high mobility group box-1 (HMGB-1) and ATP." (PMID 35844506, 2022). "The HMGB1/TLR4 axis ultimately modifies the intrinsic tumor properties and host immune response in the tumor microenvironment, leading to breast cancer metastasis." (PMID 35637945, 2022). "For instance, HMGB1 can induce ICD through interaction with TLR4, which determines the chemo- or radio-resistance of breast cancer." (PMID 35637945, 2022). "However, whether HMGB1 functions as a CpG ODN binding protein in breast cancer is not well known." (PMID 35637945, 2022). "Experimental studies have shown that CDKN2A, PSAT1, HMGB1, ELAVL1, and SLC7A11 were up-regulated in TNBC, ASNS and LAMP2 were up-regulated in breast cancer and CAV1 was down-regulated in breast cancer, and HELLS was up-regulated in other tumors." (PMID 36568247, 2022). "Although our study offers new insight into the mechanisms of HN1L in breast cancer metastasis, the specific regulatory mechanisms of the interactions among HN1L, HSPA9 and HMGB1 need further study." (PMID 33191617, 2021). "HMGB1 was found to be the primary autophagy target of the XIAOPI formula, a new anti-mammary hyperplasia drug that inhibits breast cancer metastasis." (PMID 34638242, 2021). "Considering the multifaceted role of CAFs in driving the progression of breast cancer, we evaluated GPR30-mediated CAF-induced effects on TAM resistance, finding that TAM upregulated the expression and secretion of HMGB1 via GPR30/PI3K/AKT signaling in CAFs." (PMID 34182538, 2021). "In summary, we found that activated GPR30 in CAFs induced the accumulation of HMGB1, which enhanced resistance to TAM in breast cancer cells via a paracrine effect." (PMID 34182538, 2021). "Similarly, greater cytoplasmic HMGB1 expression has been reported in TN and HER-2-positive breast cancers than in HR-positive tumors; in TN breast cancer, this expression, but not nuclear HMGB1 expression, was associated significantly with TIL and CD8+ cell abundance." (PMID 34638242, 2021). "The mechanisms involved in these pro-angiogenic activities were probed in vitro using a breast cancer cell line, (MCF-7), stably infected with the HMGB1 gene and combined with siRNA technology and assays of protein expression and cell migration." (PMID 32664328, 2020). "Autophagic CAFs abundantly release high-mobility group box 1 (HMGB1), which acts on its specific receptor, TLR4, on luminal breast cancer cells, to enhance their stemness." (PMID 33050237, 2020). "Additionally, in our cohort, intrapleural HMGB1 from lung cancer patients (70.05 ng/ml ± 24.70) was significantly elevated compared to levels observed in ovarian cancer patients (21.01 ng/ml ± 3.54; p = 0.025) and raised compared to breast cancer patients (34.50 ng/ml ± 7.38; p = 0.057)." (PMID 33013860, 2020).
breast carcinoma (continued). "In our current analysis of a public dataset of >1700 breast cancer samples, low RFS in patients with high geminin + HMGB1 + S100A4 (two RAGE ligands)-expressing patients was observed." (PMID 31844158, 2019). "A combination of high HMGB1 and LC3B showed a correlation with a good prognosis in breast cancer, particularly after adjuvant chemotherapy." (PMID 30134604, 2018). "HMGB1 mediates critical processes of EMT in colorectal carcinoma, gastric cancer, breast cancer, and airway epithelium cells." (PMID 28727734, 2017). "In the setting of cancer, HMGB1 signalling through its innate immune system receptors TLR2 and TLR4 (toll-like receptors 2 and 4) is important for an antitumour immune response in breast cancer patients." (PMID 26948869, 2016). "Western blot analyses was used to measure expression of ICD markers, including HSP70, CRT and HMGB1, in SK- or OXP-treated mammary carcinoma cells." (PMID 27248319, 2016). "Based upon further proteomics experiments, we found that EI001-induced apoptosis was associated with some potential ERK interactor involvements, such as HMGB1, BIRC6 and ATFM2 in breast cancer cells." (PMID 25742792, 2015). "We further analyzed the individual involvement of mammary tumor cell-derived ICD constituents (i.e., HSP70, CRT and HMGB1) in the promotion of the anti-metastatic activity of SK-TCL pulsed DCs." (PMID 26403780, 2015). "In that study, on French breast cancer patients, the 299G form of TLR4 showed reduced binding to HMGB1 and a correlation with faster relapse after radiotherapy." (PMID 21931695, 2011). "The therapeutic relevance of this immunogenic axis is particularly evident in breast cancer, where neoadjuvant chemotherapy agents induce GSDME-mediated pyroptosis accompanied by HMGB1 release, resulting in enhanced phagocytosis by macrophages and increased secretion of IFN-γ and IL-2." (PMID 41465435, 2025). "Furthermore, in ERα-positive breast cancer, tamoxifen itself can activate GPR30 on CAFs, triggering PI3K/AKT signaling that leads to the upregulation and secretion of HMGB1." (PMID 41465435, 2025). "In breast cancer, CAFs activate the PI3K/AKT pathway via the G protein‐coupled estrogen receptor (GPR30) to upregulate HMGB1 secretion; HMGB1 then induces tumor cell autophagy through the MEK/ERK pathway in a paracrine manner, strengthening tamoxifen resistance." (PMID 41354099, 2025). "Furthermore, we confirmed that HMGB1-induced EMT and increased breast cancer cell migration depend on RAGE expression." (PMID 40277915, 2025). "At the same time, the release of DAMPs, HMGB1 and ATP, were detected, suggesting that GSDME may mediate paclitaxel-induced pyroptosis in breast cancer cells through the caspase-9/caspase-3 pathway." (PMID 38954046, 2024). "Moreover, HMGB1, in conjugation with TNF-α participates in the anti-tumor immune response of M1 macrophages in breast cancer." (PMID 37897664, 2024). "The TLR4 agonist, high mobility group box 1 (HMGB1), might be involved because it was largely elevated in bevacizumab-resistant breast cancer." (PMID 37108657, 2023). "Additionally, docosahexaenoic acid (DHA) has been proven to trigger MDA-MB-231 breast cancer cell pyroptosis via the caspase-1/GSDMD pathway, inducing IL-1β secretion, translocation of HMGB1 to the cytoplasm, and pore formation in the cell membrane." (PMID 38016064, 2023). "Similarly, CSCs express TLR2 and its ligand high-mobility group protein 1 (HMGB1), and this autocrine loop participates in DOX resistance development in breast cancer." (PMID 36359776, 2022). "HMGB1, serving as a key biomarker of ICD, has been demonstrated in breast cancer." (PMID 35637945, 2022). "Compared to TLR2/4, clarified reports about the interaction of TLR9 with HMGB1 in breast cancer is still absent." (PMID 35637945, 2022). "Notably the interaction of HMGB1 with the TME components, such as neutrophils, macrophages, CAFs and MSCs, also contributes to the metastasis of breast cancer cells." (PMID 35637945, 2022).
breast carcinoma (continued). "HMGB1-mediated PD-L1 expression in breast cancer through the PI3K/AKT signaling pathway, however, has not been investigated." (PMID 35610613, 2022). "The HMGB1 and RAGE ligation activates EMT phenomenon and induces tumor growth in breast cancer." (PMID 35610613, 2022). "HMGB1 and HMGN1 are important nuclear DAMPs, and their translocation to the cytoplasm can activate proinflammatory signaling by binding to PRRs, resulting in TIL influx in breast cancer." (PMID 35444934, 2022). "Furthermore, MIFs release impacts host immune responses in the TME by regulating the HMGB1/TLR4/NF-κB axis 61, and all these interactions contribute to breast cancer metastasis." (PMID 35637945, 2022). "In the present study, we showed that oleandrin treatment triggered breast cancer cell ICD by inducing calreticulin (CRT) exposure on cell surface and the release of high-mobility group protein B1 (HMGB1), heat shock protein 70/90 (HSP70/90), and adenosine triphosphate (ATP)." (PMID 33762577, 2021). "Gemcitabine, used to treat breast cancer recurrence, induces the release of characteristic immunostimulatory DAMPs, such as HMGB1, CRT, and HSP70, in bladder cancer cells, but does not cause ICD of these cells." (PMID 34638242, 2021). "In a breast cancer model, docetaxel administration did not induce HMGB1 or ATP secretion or cell death, and tumor cells were not killed by ICD." (PMID 34638242, 2021). "HMGB1 secretion promotes fibroblast activation via receptor for advanced glycation end products (RAGE)/aerobic glycolysis, and activated fibroblasts promote breast cancer metastasis via an increase in lactate." (PMID 34638242, 2021). "PARylated PARP-1 is accompanied by obvious upregulation of HMGB1 and LC3II in breast cancer cells." (PMID 33158052, 2020). "Furthermore, miR-129-5p/HMGB1 axis and NONHSAT101069/miR-129-5p axis were found to regulate the radiosensitivity and epirubicin resistance of breast cancer cells, respectively." (PMID 31999936, 2020). "Further analysis of TCGA and METABRIC databases also revealed that basal-like breast cancer patients show higher levels of HMGB1 expression in primary tumors than non-basal-like breast cancer patients." (PMID 32943604, 2020). "In breast cancer patients, the presence of intranuclear HMGB1 in tumor cells (that is, non-secreted HMGB1) is a favorable prognostic factor and negatively correlates with infiltration of Tregs or tumor-associated macrophages." (PMID 31379812, 2019). "DHA-treated breast cancer cells triggered increased caspase-1and gasdermin D activation, enhanced IL-1β secretion, translocated HMGB1 towards the cytoplasm, and membrane pore formation when compared to untreated cells, suggesting DHA induces pyroptosis programmed cell death in breast cancer cells." (PMID 29386662, 2018). "Knockdown of HMGB1 modulates telomere homeostasis by downregulating expressions of telomere-binding proteins TTP1 and TRF1, thereby initiating apoptosis and increasing radiosensitivity in human breast cancer cells." (PMID 28969092, 2017). "Likewise, radiation therapy also induces cardinal signs of ICD, including cell death and release of ATP and HMGB1 in multiple carcinoma types, including MDA231 breast cancer cells." (PMID 28122343, 2017). "Although we have also previously shown this in primary myeloid cells, we did not see an effect of HMGB1 on breast cancer cells in vitro." (PMID 26392082, 2015). "Moreover, regardless of HMGB1, TLR4 is associated with a poor prognosis and chemotherapy resistance in breast cancer." (PMID 40727252, 2025). "Likewise, HMGB1/TLR4/NF-κB signaling mediates metastasis and enhances inflammatory cytokine production in breast cancer, while drug-resistant myeloma cells exhibit increased HMGB1 release, whereby silencing HMGB1 diminishes NF-κB phosphorylation and restores drug sensitivity." (PMID 41465435, 2025).